TSG101 (tumor susceptibility 101)
Diseases named in the same sentence as TSG101 in open-access papers (continued):
Sharing a sentence is not in itself a finding about the gene and the disease.
cancer (65 papers, 2008 to 2026). A tumor composed of atypical neoplastic, often pleomorphic cells that invade other tissues. "Ubiquitin-conjugating enzyme E2 variant (UEV) and lactate/malate dehydrogenase (UEVLD), also known as UEV3, is a human paralogue of Tsg101 with apparent associations to cancer, innate immunity, NF-κB signaling, and autophagy." (PMID 40571836, 2025). "The mammalian Tumor Susceptibility Gene 101 (TSG101) encodes a protein with diverse functions that control the proliferation and survival of cells, but its role in malignant transformation and cancer development has remained enigmatic." (PMID 40624726, 2025). "Equally, the down-regulation of TSG101 (Tumour susceptibility gene 101 protein), which regulates vesicular traffic, seems to be an often-cited protein in cancer-related EV studies." (PMID 39766158, 2024). "In future work, it will be interesting to investigate the association of AKTIP with cancer, because in tumorigenesis cell division is altered and since an implication in cancer has been described for TSG101 and other ESCRT factors." (PMID 34449766, 2021). "As a component of the ESCRT-1 complex, TSG101 deficiency in cancer cells was accompanied by growth inhibition, cell cycle arrest, apoptosis, and an increased abundance of p21 mRNA and protein." (PMID 34863175, 2021). "In future work, it will be interesting to explore if the AKTIP association with the ESCRT machinery has an impact on cancer, which has been indicated for TSG101 and more recently reported for the ESCRT III subunit CHMP4C." (PMID 34449766, 2021). "Tumor susceptibility gene 101 (Tsg101) was initially linked to tumorigenesis in various animal and human cancer models." (PMID 32839388, 2020). "Sequence analysis of this isoform revealed that it is the well-documented cancer-associated aberrantly spliced TSG101 isoform, the so-called TSG101∆154-1054 (abbreviated as TSG∆154-1054 hereafter)." (PMID 30759747, 2019). "TSG101 is an established cancer-associated gene and aberrantly spliced TSG101 mRNAs have been reported in various kinds of cancers." (PMID 30759747, 2019). "The tumour susceptibility gene 101 (TSG101) is reported to play important roles in the development and progression of several human cancers." (PMID 30450735, 2019). "The vertebrate ept gene homolog, TSG101, was first identified based on its ability to inhibit cell transformation and by its apparent mutational inactivation in some cancers." (PMID 19787055, 2009). "Tumor Susceptibility Gene-101 (TSG101) promotes the endocytic degradation of transmembrane proteins and is implicated as a mutational target in cancer, yet the effect of TSG101 loss on cell proliferation in vertebrates is uncertain." (PMID 19787055, 2009). "Here we aimed to explore whether EBV impacts on the alternative splicing of TSG101 (tumor susceptibility gene 101), a frequent target of cancer-specific splicing." (PMID 35269659, 2022). "On the other hand, TSG∆154-1054 may cause malignancy, since it increases full-length TSG101, which significantly promotes invasion and metastasis in cancer cells." (PMID 35269659, 2022). "TSG101 is essential for cell proliferation and survival, while its overexpression is closely associated with aggressive metastasis and progression in various cancers." (PMID 34204574, 2021). "For example, the TSG101 TSGΔ154-1054 splice variant is aberrantly expressed in a range of human cancers and could be potentially targeted in these malignancies." (PMID 34440370, 2021). "At present, there is no conclusive evidence from experimental models or human tissues in support of the notion that deficiency in TSG101 or a functional loss of the protein could contribute to the genesis and progression of cancer." (PMID 32075127, 2020).
cancer (continued). "The direct competition between TSG101 and TSGΔ154-1054 for interaction with Tal demonstrates a novel mechanism for posttranslational protein regulation; and, by this means TSGΔ154-1054 is implicated in the TSG101-associated oncogenic events and therefore, be a potential target for cancer therapy." (PMID 26811492, 2016). "For this reason, TSG101 has long been considered a tumor suppressor factor responsible for genetic stability and regulation of the cell cycle, and its mutations may lead to the disruption of these processes and, as a result, cancer development." (PMID 38607019, 2024). "Furthermore, the monoubiquitination of the cancer stem cells marker CD133 (prominin-1) promotes its secretion into extracellular vesicles by facilitating the interaction of CD133 with the vesicular sorting protein tumor susceptibility gene 101 (TSG101)." (PMID 32344852, 2020). "The ESCRT-I complex, composed of Tumor Susceptibility Gene 101 (Tsg101), VPS37, VPS28 and Multivesicular body subunit 12 (Mvb12), serves as a pleiotropic regulator in cancer pathogenesis." (PMID 40746890, 2025). "More importantly, the activation of the PI3K/AKT pathway and the survival of cancer cells was dependent on the sustained overexpression of TSG101 in tumors." (PMID 40624726, 2025). "This suggests that TSG101 has persistent pro-tumorigenic functions during cancer initiation, progression, and maintenance of established tumors." (PMID 40624726, 2025). "Compared to adjacent normal mammary glands, TSG101-overexpressing carcinomas show higher levels of ERBB3, HRAS, and active AKT (left)." (PMID 40624726, 2025). "It is suggested that TSG101 is an important factor in maintaining cellular homeostasis and that disturbances in its function lead to cancer transformation." (PMID 38607019, 2024). "TSG101 knockdown in BC cells induces apoptosis and inhibits proliferation, suggesting that TSG101 is a potential therapeutic target in cancer." (PMID 37108371, 2023). "Exosomes carry specific proteins (CD9, CD81, CD63, ALIX, TSG101, and HSP70), nucleic acids (DNA, miRNA, lncRNA, and circRNA), lipids, and metabolites with cancer information, making them potential cancer diagnostic biomarkers." (PMID 37016296, 2023). "On the other hand, exosomal proteins, such as CD63, CD9, TSG101, and EpCAM, reflecting significant information about the cancer microenvironment, are highly enriched in exosomes derived from cancer cells." (PMID 38005527, 2023). "Our results imply TSG101 as a therapeutic target to achieve synthetic lethality in cancer treatment." (PMID 36124865, 2022). "Altogether, our results showed that EhVps23 overexpression increases the virulence of trophozoites, resembling cancer cells that overexpress TSG101." (PMID 35360117, 2022). "Knockdown of syntenin-1 impaired the release of sEVs from cancer cells and downregulated the expression levels of exosomal markers, including TSG101, HSP70, and ALIX, in sEVs." (PMID 35136055, 2022). "How the accumulation of TSG101 contributes to cancer is likely a function of its role in autophagy-mediated protein degradation." (PMID 34440370, 2021). "Using TSG101 pre-mRNA as a model substrate of cancer-specific aberrant mRNA re-splicing, we demonstrate that the deposition of the EJC safeguards against the deleterious over-splicing event." (PMID 34204574, 2021). "Inferred by the detection of TSG101, both cancer cell- and milk-derived EVs were stable under acidic conditions." (PMID 34168137, 2021). "Using TSG101 pre-mRNA, we previously discovered cancer-specific re-splicing of mature mRNA that generates aberrant transcripts/proteins." (PMID 34204574, 2021).
cancer (continued). "Common EV markers (CD63, TSG101) and disease-specific EV-associated proteins (PD-L1, GPC-1) were readily detected following isolation by the ACE chip from either spiked EV or donor cancer samples." (PMID 33224932, 2020). "To sense the systemic NK cell status in cancer patients, we developed an immune enzymatic test (NKExoELISA) that measures plasma NK-cell-derived exosomes, captured as tsg101+CD56+ nanovesicles." (PMID 32231660, 2020). "In the final section of the review, we summarize critical issues that need to be addressed to gain a better understanding of biologically significant roles of TSG101 in cancer." (PMID 32075127, 2020). "In contrast, a sustained overexpression of TSG101 in primary and untransformed immortalized cells, and even in cancer cell lines, often results in cell death." (PMID 32075127, 2020). "A potential role of post-translational mechanisms that control the expression of the TSG101 protein in cancer is being discussed." (PMID 32075127, 2020). "If proven correct using in vivo cancer models or human specimens, the proposed mechanism would imply that TSG101 levels should be generally lower in cancers that overexpress MDM2 or lack p19Arf." (PMID 32075127, 2020). "More importantly, the 5-year survival rate of patients is significantly lower (33%) when their cancer tissues exhibited higher levels of TSG101 compared to patients with a low expression of this protein (53%)." (PMID 32075127, 2020). "To date, a growing body of evidence has indicated that TSG101 is overexpressed in various tumors, suggesting that TSG101 contributes to the promotion of cancers." (PMID 30675171, 2019). "The TSG101∆154-1054 protein protects the full-length TSG101 protein from ubiquitin-mediated degradation, implicating TSG101∆154-1054 protein in the progression of cancer." (PMID 30759747, 2019). "TSG∆154-1054 plays a key role in promoting the metastasis of NPC via the stabilization of TSG101, which has recently been suggested to be used as a cancer biomarker." (PMID 30759747, 2019). "TSG101 (Tumor susceptibility 101) gene and its aberrantly spliced isoform, termed TSG101∆154-1054, are tightly linked to tumorigenesis in various cancers." (PMID 30759747, 2019). "The aberrant TSG101∆154-1054 mRNA is generated from cancer-specific re-splicing of mature TSG101 mRNA." (PMID 30759747, 2019). "Despite these alternative degradation routes in controlling the TSG101 amount, increased levels of the TSG101 protein are nevertheless detected in a variety of cancers." (PMID 30759747, 2019). "Although there are several alternate degradative routes governing the amount of TSG101, increased TSG101 protein is still frequently shown in a variety of cancers." (PMID 26811492, 2016). "It has been known that TSG101 critically controls cell proliferation in both mouse embryonic tissues and human cancer cells." (PMID 26811492, 2016). "Numerous reports agree on the increased frequency of TSG101 splicing abnormalities in cervical, lung, prostate, and other cancers." (PMID 26811492, 2016). "Identification of TSG101 in our screen suggested a broader role of the entire ESCRT-I complex in the regulation of uptake of anti-miR-21 by cancer cells." (PMID 25550434, 2015). "Knockdown of TSG101 improved productive uptake of anti-miR-21 across multiple cancer cell types in tissue culture experiments, yet it was unclear if TSG101 also has an important role in regulating oligonucleotide uptake in vivo." (PMID 25550434, 2015). "Although the overexpression of PEG10 and TSG101 in cancer cells has been previously studied, their expression in SC/ASC and AC of the gallbladder has yet to be identified." (PMID 24944680, 2014). "A link between Tsg101 function and the uncontrolled growth characteristic of cancer cells is suggested by a study in which Tsg101 was inactivated by mRNA antisense transcripts, which led to increased colony formation in soft agar." (PMID 21892266, 2008).
cancer (continued). "Moreover, experiments on human cancer cell lines from patients with breast, prostate, renal, ovarian, and hepatocellular carcinomas demonstrated that TSG101 is required for the growth and survival of malignant cells." (PMID 40624726, 2025). "Several studies have highlighted the implication of the ESCRT type I TSG101 in cancer." (PMID 41227326, 2025). "In addition, the frequency of FLOT1, FLOT2, and TSG101 proteins was higher in cancer cell-line-derived exosomes when compared to control cell-line-derived exosomes." (PMID 38529947, 2024). "To test this hypothesis, we performed siRNA screening of repressor candidates based on cancer-specific mRNA re-splicing activity of the TSG101 pre-mRNA." (PMID 34204574, 2021). "TSG101 is an essential protein for the clearance of potentially toxic organelle remnants and protein aggregates and its aberrant splicing has been shown to play a role in cancer progression and tumorigenesis in multiple malignancies." (PMID 34440370, 2021). "Neither haploinsufficiency nor a complete deletion of both Tsg101 alleles in somatic tissues of genetically engineered mice, such as the mammary epithelium, led to the development of benign neoplasms or cancer." (PMID 32075127, 2020). "The elevated expression of TSG101 in cancer compared to normal tissues may support the notion that TSG101 plays a role at particular stages of cancer initiation or progression." (PMID 32075127, 2020). "More recent observations from several cancer research teams suggest that TSG101 might function as an oncoprotein." (PMID 32075127, 2020). "Similar to TAL, it is currently unknown whether a deregulated expression of MGRN1 significantly contributes to the expression and oncogenic properties of TSG101 in cancer." (PMID 32075127, 2020). "Consequently, the biological relevance of these multifaceted functions of TSG101 for normal development, differentiation, and tissue homeostasis, as well as potential roles of TSG101 in cancer are poorly defined." (PMID 32075127, 2020). "On the mechanistic level, the reduced migratory features of cancer cells with a knockdown of TSG101 might be a consequence of impaired trafficking of c-SRC to focal adhesions, as well as a loss of Focal Adhesion Kinase, MAPK, and STAT3 activation." (PMID 32075127, 2020). "Moreover, despite findings demonstrating that Tsg101 and ALIX can interact, Tsg101 seems to play a direct role in cancer, whereas the function of ALIX is generally associated with programmed cell death." (PMID 26861306, 2016). "TSG101 protein is highly and aberrantly expressed in various human cancers." (PMID 26811492, 2016). "In our observation, inhibition of Tal due to the overexpression of TSGΔ154-1054 in cancer cells may add to the effect of VPS28 to effectively prevent TSG101 degradation." (PMID 26811492, 2016). "Finally, knockdown of TSG101 increased uptake of anti-miR-21 by cancer cells in vivo following systemic delivery." (PMID 25550434, 2015). "Collectively, these results support the hypothesis that TSG101 regulates anti-miR-21 uptake by cancer cells both in vitro and in vivo." (PMID 25550434, 2015). "Therefore, TSG101 in cancer cells might counteract the perforin‐induced membrane damage, and thus act as a cellular defense mechanism against CTL induced killing." (PMID 41273303, 2026). "Moreover, excess levels of TSG101 are required for the survival of carcinoma cells in vivo." (PMID 40624726, 2025). "Furthermore, alternative and/or mis-splicing of ESCRT genes that affect autophagy play roles in the pathogenesis of several diseases, including TSG101 in cancer and CHMP2B and VPS4B mis-splicing in the pathogenesis of FLTD and dental dysplasia I (respectively)." (PMID 34440370, 2021).
cancer (continued). "TSG101 mRNA is frequently re-spliced in various cancer tissues for unknown reasons." (PMID 34204574, 2021). "As stated in the opening paragraph of this review, initial reports about a loss of the TSG101 gene in human cancers could not be confirmed." (PMID 32075127, 2020). "A multitude of evidence revealed that distinct exosomal proteins, e.g., Rab, GTPases, ESCRT, CD9, CD81, CD63, flotillin, TSG101, ceramide, Alix, tetraspanins, and integrins, could be used for cancer detection and consideration of clinical outcomes in cancer patients." (PMID 33168028, 2020). "The majority of upregulated proteins have been previously linked to tumorigenesis or cancer homeostasis, including signaling molecules (integrin αV, GNAQ, GNA11, the latter two being associated with UM tumorigenesis), molecular chaperon (HSPB1), and an ESCRT-I complex subunit (i.e., TSG101)." (PMID 33050649, 2020). "To further validate this binding, we used GFP‐Trap beads to immunoprecipitate GFP‐tagged SPHK1 from cancer cells and we found that SPHK1 does indeed interact with TSG101." (PMID 35289120, 2022). "Thus, the aberrant accumulation of TSG101 rather than its loss is linked to cancer in humans." (PMID 34440370, 2021). "TSG101, an ESCRT-I protein, played extensive roles in modulating cell proliferation, apoptosis, actin remodeling, and EGFR and JAK/STAT in cancers." (PMID 33959493, 2021). "Other molecules, such as RAB27A/B, TSG101, and TSAP6, have also been shown to be involved in the secretion of EVs from cancer cells." (PMID 32932657, 2020). "In human cancer cell lines, the adaptor protein Cep55 is essential for the MB localization of ALIX and Tsg101, which in turn promote the assembly of the ESCRT-III abscission complex." (PMID 32269212, 2020). "Knockdown of TSG101, along with a second ESCRT-I protein, VPS28, enhanced uptake of anti-miR-21 across multiple cancer cell lines." (PMID 25550434, 2015). "TSG101, one of the major ESCRT-I constituents, was identified in an unbiased, rigorously controlled shRNA depletion screen in cancer cells treated with anti-miR-21 compound." (PMID 25550434, 2015). "Of the 18 candidate risk markers, 11 and 7 showed hyper and hypomethylation in cancer, respectively, with TSG101 and the pre-mRNA splicing factor SFRS6 both undergoing hypermethylation in cancer." (PMID 20019873, 2009). "The HsVps35, TSG101, and CHMP6 (orthologous of EhVps35, EhVps23, and EhVps32) proteins have been widely studied in multiple cellular processes, such as cell migration, secretion, and cell proliferation in cancer." (PMID 39397861, 2024). "WB results validated the expression of EVs specific markers and cancer specific marker, we obtained distinct bands for CD9, TSG101 and PDL-1 verifying the presence of the EVs specific markers and cancer specific marker, respectively, while calnexin as an EVs’ negative marker." (PMID 35624582, 2022). "Absence of impact on this signaling in Tsg101-KD cells is contrasting to what was previously observed in the cancer HeLa cellular model." (PMID 34330273, 2021). "In general, PCa-associated exosomes procured from clinical samples reveal cargo that contains cancer-related proteins such as CD9, CD81, and TSG101, Annexin A2, Fatty Acid Synthase (FASN), and prostate-specific membrane antigen (PSMA: a PCa-specific biomarker)." (PMID 32121073, 2020). "Furthermore, both TSG101 and CD63 were detected in exosomes derived from all 3 different cancer cell lines." (PMID 27385095, 2016). "Since depletion of TSG101 and VPS28 resulted in restoration of uptake in SKHEP1 anti-miR-21 resistant clones, we asked if a similar effect could be achieved in additional cancer cells lines with inherently poor free uptake of oligonucleotides." (PMID 25550434, 2015). "Variant TSG01 transcripts lacking segments present in full-length TSG101 mRNA have been reported to accumulate in multiple types of human cancer." (PMID 24244542, 2013).